IFNG (interferon gamma)
Diseases named in the same sentence as IFNG in open-access papers (continued):
Sharing a sentence is not in itself a finding about the gene and the disease.
tumor (continued). "Remarkably, whereas spleen T cells show similar activation status independently of the treatment, tumor T cells were more activated when mice were treated with IFNγ and galectin antagonists." (PMID 28986561, 2017). "We therefore conclude that a treatment with galectin antagonists improves T-cell infiltration in the tumor, most probably because of a higher production of IFNγ-induced chemokines." (PMID 28986561, 2017). "In mouse models, the CXCL9 produced by tumor cells in response to IFNγ was found responsible for T-cell infiltration." (PMID 28986561, 2017). "Early in vivo study showed that neutralising IFNγ enhanced tumour growth, suggesting that IFNγ protects malignant lesions." (PMID 29156701, 2017). "Apigenin enhances the ability of therapeutic HPV DNA vaccination to activate IFNγ-producing CD8+ cells, implying that vaccination-induced IFNγ and apigenin act together to kill tumor cells." (PMID 28526810, 2017). "On the contrary, T cells proliferated, expressed activation markers, secreted IFNγ and even eliminated tumor cells in the spheroids." (PMID 28827632, 2017). "Pretreatment of tumour cells with IFNγ slightly enhanced the activation of CD8+ T cells by Ma-Mel-36_bulk and Ma-Mel-36_sens cells, whereas the T-cell-stimulatory capacity of Ma-Mel-36_res cells was not affected." (PMID 28561041, 2017). "IRF-1 functions both as a tumor suppressor and regulator of immune response, and is required for IFNγ-mediated TH1 differentiation in CD4+ T cells." (PMID 28642803, 2017). "The subpopulation of Ma-Mel-61h-JAK1 transfectants demonstrated de novo HLA class I surface expression after IFNγ-treatment, resulting in detection of the previously ignored tumour cells by autologous CD8+ T cells." (PMID 28561041, 2017). "In summary, suppression of GBM tumor growth correlated with reduction of immune suppressive cells (Treg and MDSC), an increase of tumor killing macrophages (M1), and reduction of markers of chronic inflammation (CCL4 and IFNγ) in the tumor microenvironment." (PMID 28512255, 2017). "NK cells are a central component of the innate immune system, secreting different cytokines like IFNγ, interleukin-10 or TNFα to stimulate other immune cells, and are capable to directly destroy tumor cells." (PMID 28690853, 2017). "Taking together these data, we conclude that, in this mouse model, inhibition of galectin-3 reduces the tumor growth by boosting IFNγ intratumoral activity." (PMID 28986561, 2017). "Here the authors show that galectin-3 secreted by tumours binds both glycosylated IFNγ and glycoproteins of the tumour extracellular matrix, thus avoiding IFNγ diffusion and the formation of an IFNγ-induced chemokine gradient required for T cell infiltration." (PMID 28986561, 2017). "Our results demonstrated that penfluridol treatment resulted in 54% and 49% reduction of CCL4 and IFNγ respectively, indicating suppression of inflammation in the tumor microenvironment." (PMID 28512255, 2017). "The interaction between CD1d-glycolipid complex and the invariant TCR of iNKT cells stimulates interferon gamma (IFN-γ) production and the secretion of a large number of other cytokines (e.g. IL-12, IL-4, IL-17) that promote tumor eradication." (PMID 28549432, 2017). "We have recently demonstrated that the inhibitory checkpoint molecule PD-L1 is upregulated on Tasmanian devil (Sarcophilus harrisii) facial tumor cells in response to the interferon-gamma cytokine." (PMID 28515726, 2017). "Within the tumor microenvironment, MSCs suppressed the ability of DC-mediated T cell mechanisms including IFNγ secretion and tumor cytotoxicity by reducing the amount of available cysteine excretion through a STAT3 mechanism." (PMID 29181035, 2017). "Modeling of the data suggests that the effect of IFNγ on NK cell-mediated tumor lysis is mostly dependent on changes in MHC-class I and ICAM-1 expression." (PMID 28428785, 2017).
tumor (continued). "Tumor pieces were immersed for 6 h in media supplemented with glycosylated IFNγ alone or with galectin-3 antagonists." (PMID 28986561, 2017). "Factors that initiate these pathways, including TLR, IL4, IL13, TGFB and IFNG, are expressed by tumour stroma and activated T-cells." (PMID 28193698, 2017). "Using these cancer cells corresponding to six different types of pediatric malignancies, we evaluated the effects of IFNγ treatment in tumor cell sensitivity to NK cell-mediated lysis." (PMID 28428785, 2017). "Th1 (T helper 1 cells) produced IFN-γ(interferon gamma) to promote anti-microbial and anti-tumor response, and Tregs suppressed the immune response of T cells in both physiological and pathological state." (PMID 28029650, 2017). "Beside its role as tumor-suppressor, miR-16 was recently shown to affect NK function by repressing IFNγ expression, and to promote M1 pro-inflammatory type macrophage polarization, affecting T cell activation." (PMID 28081700, 2017). "T-cell recruitment towards the tumor requires a chemokine gradient of the critical IFNγ-induced chemokines CXCL9/10/11." (PMID 28986561, 2017). "The increase of NK cell-mediated IFNγ production and cytotoxic activity against tumor cells results in an increased ability of NK cells to perform an efficient editing of DCs." (PMID 28503177, 2017). "Expanded TIL populations were tested for tumour reactivity by subjecting the supernatant of TIL:autologous tumour specimen co-culture to IFNγ ELISA to detect IFNγ release." (PMID 28146145, 2017). "The exogenous IL-2 induces NK cell proliferation, activates cytotoxic immune responses against the tumor and induces expression of certain cytotoxic cytokines, such as interferon-gamma (IFNgamma) and transforming growth factor-beta." (PMID 29312320, 2017). "NK cells played an anti-tumor role through ADCC as well as by providing IFNγ stimulation to CD8+ T cells." (PMID 29163850, 2017). "Accumulating studies suggested that MSI-positive tumours presenting neoantigens promote the release of IFNγ from tumour-infiltrating lymphocytes (TILs), and the released IFNγ upregulates PD-L1 expression in immune cells and tumours." (PMID 29170499, 2017). "A recent study showed that co-targeting mTOR and PD-L1 enhances tumor control by increasing the IFNγ production capacity in peripheral and tumor-infiltrating CD8 T cells in a syngeneic oral cavity cancer model." (PMID 28822012, 2017). "Due to the high levels of IFNγ secreted by NK cell infusion products, we sought to determine the effects of IFNγ on NK cell interactions with the tumor cells." (PMID 28428785, 2017). "In this regards, the combined action of IFNγ and TNFα has been demonstrated to destroy tumour cells and their stroma thereby essentially contributing to the eradication of established mouse tumours." (PMID 28561041, 2017). "Vδ2+ cells produce significant amounts of pro-inflammatory cytokines like TNFα and IFNγ in order to counteract bacterial infections or tumour development." (PMID 28076364, 2017). "T-cell responses were investigated by interferon-gamma (IFN-γ) enzyme-linked immunospot and cytotoxic T lymphocyte (CTL) assays using peripheral blood mononuclear cells (PBMCs) in 47 patients, and tumor-infiltrating lymphocytes in 8 of 47 patients with HCC." (PMID 28114424, 2017). "Future studies would be needed to investigate if BRB-enhanced NK infiltration was a compensatory mechanism to rescue the decreased IFNγ production, in order to maintain the tumor surveillance of NK cells." (PMID 28861089, 2017). "IFNγ is a cytokine secreted by tumor–infiltrating T cells and induce PD-L1 expression by stimulating the JAK/STAT signaling pathway in myeloid leukemia cells." (PMID 29259270, 2017). "The most well-known mechanism of PD-L1 induction on tumor epithelial cells is cytokines such as IFNγ produced by adaptive immune cells in the tumor microenvironment (‘adaptive immune resistance’)." (PMID 28460462, 2017).
tumor (continued). "The anti-photocarcinogenesis effect of GSPs in the wild-type mice was found to be associated with the reduced secretion of immunosuppressive cytokines and increased secretion of immunostimulatory cytokine IFNγ in the tumor microenvironment." (PMID 28548949, 2017). "Interferon-gamma expression at primary tumor sites can drive DC maturation and rapid migration to DLN for Ag-presentation." (PMID 29109732, 2017). "Decrease in CCL4 as well as IFNγ with penfluridol treatment was also observed indicating decrease in overall tumor inflammation." (PMID 28512255, 2017). "As such the direct cytotoxic effects of CD8+ T cells mediated by release of cytolytic granules or death receptor engagement are an essential but most likely insufficient part of the overall anti-tumour response that also depends on the secretion of IFNγ." (PMID 28561041, 2017). "Due to the high IFNγ secretion of NK cell infusion products, a better understanding of the NK ligands on tumor cells and how they are affected by IFNγ is essential to optimize NK cell immunotherapy." (PMID 28428785, 2017). "In relatively immunogenic tumors, RT alone was able to elicit antitumor T cells that infiltrated the tumor and produced interferon-γ (IFNγ), which in turn induced PD-L1 expression on tumor cells." (PMID 28348554, 2017). "In MMTV-neu animals, lapatinib promotes tumor infiltration of IFNγ-secreting CD4+ and CD8+ T cells in a Stat1-dependent manner." (PMID 29403144, 2017). "The principal cytokine produced by γδT cells in humans is IFNγ, with an anti-viral, anti-bacterial, and anti-tumor immunity role." (PMID 28944217, 2017). "Metastasis Ma-Mel-36 developed after the patient had been treated with recombinant IFNα and a combination of dacarbacine/IFNα/interleukin (IL) 2, suggesting activated tumour-reactive T cells selectively enriched the IFNγ-resistant cell subpopulation." (PMID 28561041, 2017). "Four days after ACT, we observed a strong reduction in the number of apoptotic TILs, indicating the involvement of IFNγ in triggering T-cell apoptosis at the tumor site." (PMID 29123081, 2017). "Alterations affecting genes of the IFNγ signalling cascade were more frequent in metastatic samples compared with primary tumours and were detectable in metastases from patients receiving neo-adjuvant IFNα and from patients without treatment." (PMID 28561041, 2017). "By adding galectin antagonists to the IFNγ-supplemented medium, we expected to improve the diffusion of IFNγ in a tumor microenvironment supposedly enriched in galectins, thereby increasing CXCL9 expression." (PMID 28986561, 2017). "Although some tumor cells constitutively express PDL1, other tumor cells only express PDL1 after induction by IFNγ." (PMID 28938530, 2017). "The cytokines like IL-12 and IFNγ have an anti-tumor role, while the cytokines like IL-6, IL-17, and IL-23 are pro-tumor." (PMID 28337150, 2017). "Similar to IFNγ production, a significant fraction (48% in the surrounding tissue and 62% in the tumour) of PD-1+ CD8+T cells expressed CD107a illustrating their overall competence to degranulate within the tumour." (PMID 28128200, 2017). "Radiotherapy can modulate the immune system to promote CD8+ T cells to attack tumor cells through multiple mechanisms including the release of stimulatory cytokines such as IFNγ." (PMID 27932443, 2017). "The presence of IFNγ-producing cells in the primary tumor mass is inversely correlated with tumor growth." (PMID 29109732, 2017). "Such induction occurs in the tumor microenvironment when solid tumors are infiltrated by activated IFNγ-secreting T cells." (PMID 28938530, 2017). "Tumor growth was significantly inhibited by the combination of h11c-treated DC and IFNγ treatments ([h11c-DC]+IFN), relative to all other treatments." (PMID 29190690, 2017). "This was further demonstrated when gating on individual cell types, where averages of 45, 22 and 4% of CD8+T cells, NK and NKT cells respectively produced IFNγ in tumours of NKG2D-WT mice." (PMID 28128200, 2017).
tumor (continued). "Our recent studies showed that bortezomib can also increase the cytoplasmic and nuclear phosphorylation of NFκB p65 in CD8+T cells while maintaining IFNγ secretion to improve FasL-mediated tumor lysis." (PMID 28052005, 2017). "Due to the opposing effects reported for IFNγ on tumor sensitivity to NK cells, we evaluated a panel 22 tumor cell lines from the pediatric preclinical testing program corresponding to different tumor types." (PMID 28428785, 2017). "Of note, bortezomib treatment restored IFNγ synthesis and inhibited metastasis in tumor-bearing mice even in the presence of neutralizing antibodies to IL-12 and IL-15." (PMID 28052005, 2017). "IFNγ secretion by NK cells has been shown to contribute to the tumor adaptive immune resistance response by upregulating the expression of HLA-I and PD-L1 in HER2+ breast cancer cells in vitro and in vivo." (PMID 29181007, 2017). "Experimental animal studies highlighted the importance of NK cell-mediated secretion of IFNγ in tumor rejection." (PMID 28348567, 2017). "We conclude that inhibition of galectins releases the IFNγ trapped in the matrix of human tumor biopsies, facilitating IFNγ diffusion, and consequently increasing CXCL9 expression." (PMID 28986561, 2017). "CM was produced through activating astrocytes either by co-culturing them in the presence of the tumor cells (CM: A 231BR) or by treatment with IFNγ and TNFα (CM: A IFNγ + TNFα), two agents known to activate astrocytes." (PMID 28008153, 2017). "Our results show upregulation of PD-L1, ICAM-1, MHC-class I, HLA-DR, CD95/FasR, and CD270/HVEM after IFNγ treatment, this upregulation is variable across different tumor types." (PMID 28428785, 2017). "We performed Elispot assays for IFNγ secreting capacity of CD8+ T cells derived from the draining lymph nodes of tumor-bearing WT or CCR2−/− mice 7 days post-IR, using MC38 cancer cells as sources of tumor antigen." (PMID 29170400, 2017). "Although it has been used to treat tumors due to its immunostimulatory function, paradoxically IFNγ, has recently been found to promote tumor progression by upregulating checkpoint inhibitors." (PMID 29088818, 2017). "To further examine the role of the extracellular matrix in IFNγ trapping by galectin-3, we partially degraded the ECM by injecting in the center of the tumor a low dose of collagenase D together with IFNγ." (PMID 28986561, 2017). "IFNγ was initially identified to play a significant role in the detection and elimination of tumour cells as well as tumour surveillance by enhancing tumour cell immunogenicity." (PMID 29156701, 2017). "Under certain conditions, IFNγ plays critical role in anti-tumor host immunity and supports tumor growth." (PMID 28512255, 2017). "This is, to our knowledge, the first study to evaluate the effect of IFNγ on a broad range of NK cell ligands and across nearly two dozen cell lines representing six broad tumor types." (PMID 28428785, 2017). "From these data, we conclude that homozygous loss of JAK1 leads to loss of the IFNγ response gene set, consistent with a role for JAK1 as a tumor suppressor in this context." (PMID 29121062, 2017). "IFNγ production from 4/6 post-REP TIL samples was increased in the presence of autologous tumor cells." (PMID 29371915, 2017). "Not only the number of tumor-reactive T cells was increased but also the percentage of polyfunctional T cells producing the inflammatory cytokines IFNγ and IL-2 was increased." (PMID 28401257, 2017). "Induction of necroptosis in tumor cells by triggering RIPK3 resulted in the release of damage-associated molecular pattern molecules, subsequent dendritic cell activation, and priming of tumor antigen-specific IFNγ-producing T cell." (PMID 29312298, 2017). "The analysis of mechanism involved in NLGP mediated tumor restriction revealed the secretion of IFNγ within the NLGP treated tumor microenvironment." (PMID 28533783, 2017).
tumor (continued). "Compared to PBS controls, intra-tumoral ML-RR-CDA induced a potent Th1 (IFNγ) response in the tumor microenvironment that resulted in an in vivo anti-tumor response of the reconstituted human HNSCC tumor." (PMID 28008146, 2017). "One plausible explanation for these findings is that the restoration of a type-1 IFNγ response is related to a decrease in the immunosuppressive tumor burden." (PMID 28409322, 2017). "Responsiveness to AIT correlates to the ability of culture-expanded TIL to produce interferon- γ (IFNγ) upon tumor reexposure, as well as to the dual presence of CD4+ and CD8+ T-cells in the administered AIT product." (PMID 27974697, 2017). "We also noted that IFNγ synthesis and control of metastatic growth are both dependent on IL-12 and IL-15 signaling since the blocking of these cytokines decreased IFNγ production and increased the number of tumor pulmonary nodules." (PMID 28052005, 2017). "Altogether, these data indicate that both the tumor matrix and the extracellular galectin-3 cooperate to limit the spreading of IFNγ signaling." (PMID 28986561, 2017). "In line with this, it has been observed that NLGP causes activation of natural killer (NK) cells and NK-T cells and stimulates the secretion of interferon gamma (IFNγ) and Tumor necrosis factor alpha (TNFα) leading to tumor cell cytotoxicity." (PMID 28533783, 2017). "Tumor-infiltrating effector Th1 cells can exert direct antitumor cytolysis and secrete IFNγ, which sustains innate cell activation against cancer." (PMID 29312296, 2017). "Among IFNγ-producing cells, CD8+T cells were the dominant source of IFNγ accounting for 56.8% of IFNγ+ lymphocytes within the tumour of Klrk1+/+ mice, while NK and NKT cells represented 9.8% and 8.1% respectively." (PMID 28128200, 2017). "To optimize the use of expanded NK cells as an immunotherapy it is imperative that we better understand how IFNγ affects NK cell-mediated lysis of the tumor cells." (PMID 28428785, 2017). "Whereas IL-12 initiates tumor rejection via polarization of IFNγ-producing Th1 cells, activation of natural killer, and cytotoxic T cells, IL-23 promotes tumor progression." (PMID 28191009, 2017). "Blockades of PD-1+ and Tim-3+ were effective in restoring tumor infiltrating T-cells’ production of interferon-gamma (IFN-γ)." (PMID 29213216, 2017). "This study shows that tumor-secreted galectin-3 hijacks IFNγ in the tumor microenvironment, reducing the induction of a chemokine gradient and thereby T-cell recruitment into the tumor bed." (PMID 28986561, 2017). "To date, the efficacy of IFNγ and other cytokine-based anticancer therapies remains uncertain, due to their complex effect on both tumor cells and the tumor microenvironment." (PMID 28526810, 2017). "Since IFNγ is known to be the main inducer of PD-L1 on tumor cells and high amount of IFNγ is released in cetuximab-activated NK cell-treated DC supernatants, we wanted to know if these activated DCs also express inhibitory molecules such as PD-L1." (PMID 28674498, 2017). "All together, these data indicate that the presence of galectin-3 is a limiting factor for IFNγ-induced CXCL9/10 expression by tumor cells." (PMID 28986561, 2017). "When tumors had reached a volume of 500 mm3, IFNγ was injected in the center of the tumor, alone or in combination with galectin antagonists." (PMID 28986561, 2017). "We tentatively conclude that galectin antagonists help the diffusion of IFNγ in the tumor microenvironment by releasing it from the galectin lattices, and thereby increasing CXCL9/10 expression." (PMID 28986561, 2017). "Collectively, these findings suggest that the increased expression of IFN target genes in cluster B TAMs results, at least in part, from an elevated level of IFNγ in the tumor microenvironment." (PMID 28327095, 2017). "We also investigated the PD-L1 induction upon direct treatment of tumor cells with recombinant human IFNγ (r﻿hIFNγ)." (PMID 28801607, 2017).